HLA-DQA1 (major histocompatibility complex, class II, DQ alpha 1)
Diseases named in the same sentence as HLA-DQA1 in open-access papers (continued):
Sharing a sentence is not in itself a finding about the gene and the disease.
melanoma (6 papers, 2020 to 2025). A malignant, usually aggressive tumor composed of atypical, neoplastic melanocytes. "Depending on a person’s genetic background, homozygosity at the HLA-DQA1 locus has been reported as a potential risk factor for developing melanoma." (PMID 32592366, 2020). "Depending on an individual's genetic background, purity of the HLA-DQA1 locus may be considered a potential risk factor for the development of melanoma, having the ability to suppress melanoma cell growth, proliferation, and migration." (PMID 39969704, 2025). "Subsequent experiments were conducted to evaluate the effects of inhibiting HLA-DQA1 expression on melanoma cell proliferation, invasion, and migration." (PMID 37884883, 2023). "Other research found that class II molecules (HLA-DPA1, HLA-DPB1, HLA-DQA1, HLA-DRA, HLA-DRB1, HLA-DRB5) are important biomarkers in the occurrence and progression of melanoma tumors, and their expression levels are closely related to prognosis and immune infiltration." (PMID 39969704, 2025).
pancreatitis (6 papers, 2018 to 2025). Inflammation of the pancreas. "Recent studies identified the association of the HLA-DQA1*02:01-HLA-DRB1*07:01 haplotype with a 17% risk of developing pancreatitis in patients homozygous for the at-risk allele." (PMID 41010923, 2025). "There is a recent report indicating that the HLA-DQA1-HLA-DRB1 polymorphism is an important marker for AZA-induced pancreatitis risk." (PMID 34426870, 2021). "In the Caucasian population, thiopurine-induced pancreatitis was reported to be associated with the HLA-DQA1*02:01-HLA-DRB1*07:01 haplotype." (PMID 29923122, 2018). "For example, a Dutch study did define a genetic passport that included several loci (TPMT, NUDT15, HLA-DQA1*02:01-HLA-DRB1*07:01, and HLA-DQA1*05) associated with toxic effects from thiopurines (i.e., myelosuppression and pancreatitis) and anti-TNFα mABs (i.e., immunogenicity)." (PMID 33628180, 2020). "However, 12% of cases carried rs71542416 but were negative for HLA-DRB1∗10:01, suggesting that the SNP may be a tag for other rare HLA alleles, which is consistent with the hypothesis of Heap et al21 who showed an association between HLA-DQA1-HLA-DRB1 variants and thiopurine-induced pancreatitis." (PMID 33058932, 2021).
tuberculosis (6 papers, 2016 to 2025). A chronic, recurrent infection caused by the bacterium Mycobacterium tuberculosis. "Through differential gene expression analysis, clustering, and enrichment analysis, we identified 13 key biomarkers, including CCL2, SLC11A1, CD209, HLA-DQA1, and TIRAP, which are strongly associated with immune responses in tuberculosis." (PMID 40565607, 2025). "In humans as well, where TB has been a leading cause of death for centuries, individual single sequence variants between HLA-DQA1 and HLA-DRB1 have been strongly and repeatedly associated with M. tuberculosis infections and pulmonary TB disease in Icelandic, Russian and Croatian populations." (PMID 40855227, 2025).
Cirrhosis (5 papers, 2011 to 2025). A chronic disorder of the liver in which liver tissue becomes scarred and is partially replaced by regenerative nodules and fibrotic tissue resulting in loss of liver function. "Specifically, in cirrhosis, HLA-DQA1 exhibited an outstanding area under the curve (AUC) of 0.973, while CD27 also showed robust performance with an AUC of 0.846." (PMID 41202080, 2025). "Studies have reported that HLA-DQA1*06:01 may be a predisposing factor for HBV infection and progression to cirrhosis." (PMID 41409291, 2025). "Notably, our scRNA results revealed a novel finding: as cirrhosis progresses, HLA-DQA1 expression in macrophages tends to decrease." (PMID 41202080, 2025). "In the sub-network that is deregulated from hepatitis C, HLA-DQA1 and DQB1 are associated with development of cirrhosis, and DQB1 could be risk factors for the occurrence of HCC." (PMID 21526182, 2011). "Moreover, HLA-DQA1 and DQB1 are associated with development of cirrhosis, and DQB1 might be a risk factor for the occurrence of HCC." (PMID 21526182, 2011). "In the stratification of HLA-DQA1 for OS analysis, high expression showed significance in males, age ≤ 60 years, active viral replication-chronic carriers of HBV, cirrhosis, single nodular, low AFP levels (≤ 300 ng/ml) and A stage of the BCLC system compared with low expression." (PMID 31602270, 2019).
hepatocellular carcinoma (5 papers, 2013 to 2025). A malignant tumor that arises from hepatocytes. "Low HLA-DQA1 expression was associated with poor prognosis in hepatocellular carcinoma, lung cancer, and soft tissue sarcoma patients as its reduction indicated the presence of an immunosuppressive microenvironment and invasive disease." (PMID 37434241, 2023).
lung carcinoma (5 papers, 2020 to 2025). "Five prognostic genes, including HPSE, DENND1C, GRWD1, HLA‐DQA1, and PDXK, were identified to further develop a risk signature, which exhibited moderate power for forecasting the prognosis of lung cancer patients in training, testing, and validation sets." (PMID 41031217, 2025).
peanut allergy (5 papers, 2021 to 2023). "The alternate roles of HLA-DQA1*01:02 in the risk for peanut allergy and a favorable molecular response (Ara h 2 IgG4 levels) converge on a common mechanism of enhanced immune recognition." (PMID 34981779, 2022). "Although HLA-DQA1*01:02 was previously identified by GWAS as a risk locus for peanut allergy, the link to peanut-specific IgG4 was uncovered by studying the response of high-risk infants to a potential therapeutic intervention." (PMID 34981779, 2022). "Interestingly, the very same allele — HLA-DQA1*01:02 — was associated with peanut allergy risk in the avoidance arm of the study." (PMID 34981779, 2022). "Oral immunotherapy to food allergens is an example of controlled antigen exposure with therapeutic potential, and the relationship between HLA-DQA1*01:02 and peanut allergy provides a framework for improving our understanding of allergic sensitization and tolerance." (PMID 36466872, 2022). "However, the relationship between HLA-DQA1*01:02 may be context dependent as other studies have found that HLA-DQA1*01:02 is positively correlated with peanut allergy (OR 1.81)." (PMID 37034151, 2023). "HLA-DQA1*01:02 had a protective role with the induction of Ara h 2 epitope-specific IgG4 associated with peanut consumption during the LEAP clinical trial for prevention of peanut allergy, while it was a risk allele for peanut allergy in the peanut avoidance group." (PMID 36466872, 2022). "As the authors point out, consumption is so effective in preventing peanut allergy that it is not possible from their data to assess whether HLA-DQA1*01:02 associates with tolerance in consumers." (PMID 34981779, 2022). "Notably, we confirmed the previously reported associations with HLA-DQA1*01:02 and peanut allergy risk in the absence of oral peanut protein exposure." (PMID 34981778, 2022).
psoriasis (5 papers, 2021 to 2026). An autoimmune condition characterized by red, well-delineated plaques with silvery scales that are usually on the extensor surfaces and scalp. "Also associated with psoriasis pathogenesis: HLA-C*18, HLA-B57, HLA-DR*07, HLA-DQA1*:02:01 and DQB*:02:02." (PMID 38612637, 2024). "Genotype integration reveals that HLA-DQA1*01 and HLA-DRB1*15 genotypes are positively associated with baseline psoriasis severity." (PMID 41565778, 2026). "In a Chinese Han population, the HLA-DQA1*01:04 and DQA1*02:01 alleles were associated with an increased risk of psoriasis, whereas the HLA-DQA1*05:01 allele was found to have a protective effect against the disease." (PMID 41512531, 2026).
schizophrenia (5 papers, 2012 to 2025). A major psychotic disorder characterized by abnormalities in the perception or expression of reality. "Though the CAMs pathway was associated with schizophrenia in pathway level in both Chinese Han and European population, the significant associated CAMs genes in our dataset were different from those significant CAMs genes (HLA-DQA1, CDH4, NRXN1 and CNTNAP2) reported in European population." (PMID 26674772, 2015). "Additionally, meta-analysis found that 18 SNPs in 9 module genes had Pmeta<1×10−4, including the gene HLA-DQA1 located in the MHC region on chromosome 6, which was reported in previous studies using the largest cohort of schizophrenia patients to date." (PMID 22792057, 2012).
esophageal squamous cell carcinoma (4 papers, 2022 to 2023). Esophageal squamous cell carcinoma (ESCC) is a type of esophageal carcinoma (EC) that can affect any part of the esophagus, but is usually located in the upper or middle third. "In the case of esophageal cancer, high levels of HLA-DQA1 expression are associated with clinical characteristics and prognosis of esophageal squamous cell carcinoma." (PMID 37884883, 2023). "HLA-DQA1, a member of MHC Class II molecules, its elevated expression has been identified as an adverse indicator for worse prognosis for esophageal squamous cell carcinoma patients." (PMID 35692574, 2022). "HLA-DQA1 is a member of the MHC class II family, located on chromosome 6p21, and may be a potential prognostic biomarker for esophageal squamous cell carcinoma." (PMID 35936748, 2022).
gastric cancer (4 papers, 2014 to 2025). A primary or metastatic malignant neoplasm involving the stomach. "The first published study in a Turkish population observed univariate correlations between HLA-DQA1*01 susceptibility to gastric cancer and between HLA-DQA1*05 and protection." (PMID 38540398, 2024). "HLA-DQA1 gene copy number polymorphism was associated with gastric cancer susceptibility in the Chinese population." (PMID 31602270, 2019). "Interestingly, recent studies have demonstrated that polymorphisms occurred in HLA-DQA1 increase the risk and prognosis to lung squamous cell carcinoma and gastric cancer." (PMID 24595008, 2014).
idiopathic membranous nephropathy (4 papers, 2016 to 2023). "The associations of single nucleotide polymorphisms (SNPs) in PLA2R1 and HLA-DQA1, as well as HLA-DRB1*15:01-DQB1*06:02 haplotype with idiopathic membranous nephropathy (IMN) is well known." (PMID 30349113, 2018). "For idiopathic membranous nephropathy, SNPs in PLA2R1 (rs4664308) and HLA-DQA1 (rs2187668) have been shown to be important in Caucasians, while multiple loci are risk factors for IgA nephropathy in Asians." (PMID 27871254, 2016).
myositis (4 papers, 2014 to 2025). "Dysregulation of HLA genes including HLA‐DQA1, HLA‐A, and HLA‐G are described in DM patients and HLA gene polymorphisms were shown to be susceptibility factors in myositis." (PMID 34043263, 2021). "The HLA-DRB1*0301 and HLA-DQA1*0501 alleles have been reported as risk factors for myositis in Western populations, whereas DRB1*0803 may increase PM susceptibility among the Japanese population." (PMID 24894810, 2014). "However, the HLA-DQA1*03:03 allele was a unique risk factor for MAV in Caucasians (OR=3.87, 95% CI=1.56-9.54, p=0.002), while the known myositis risk factor, HLA-DRB1*03:01, was a protective factor for MAV (OR=0.41, 95% CI=0,18-0.94, p= 0.033)." (PMID 40895572, 2025). "Eleven women who had developed inflammatory myositis after they received silicone implants differed by increased frequency of HLA-DQA1*0102 from 76 women with myositis without silicone implants." (PMID 27634631, 2016). "The novel identification of the HLA-DQA1*03:03 allele as a unique risk factor for MAV and the protective factor of HLA-DRB1*03:01 suggests the role of a genetic predisposition in the MAV group that differs from non-MAV myositis patients." (PMID 40895572, 2025).
Sepsis (4 papers, 2018 to 2024). Sepsis is defined as life-threatening organ dysfunction caused by a dysregulated host response to infection. "Results of qRT-PCR validated the higher expression level of B2M as well as lower expression level of HLA-DQA1, HLA-DPA1, TAP1, and TAP2 in sepsis samples compared to control sample." (PMID 35685286, 2022). "Compared with healthy controls, B2M was significantly upregulated in sepsis samples yet the expression level of HLA-DQA1, HLA-DPA1, TAP1, and TAP2 was significantly lower in sepsis specimens." (PMID 35685286, 2022). "Results of qRT-PCR validated the higher expression level of B2M as well as lower expression level of HLA-DQA1, HLA-DPA1, TAP1, and TAP2 in sepsis samples compared to control samples." (PMID 35685286, 2022). "In contrast to the investigated HLA-DR genes, no significant sepsis-induced changes were detected in transcription of HLA-DQA1 and HLA-DQB1 (p = 0.81 and p>0.99)." (PMID 30212590, 2018).
squamous cell carcinoma (4 papers, 2017 to 2025). A carcinoma arising from squamous epithelial cells. "A reduced risk of squamous cell carcinoma was seen with both HLA Class I (HLA-B*15 (OR = 0.55, P = 4.78 × 10−6)) and HLA Class II alleles (HLA-DQA1*0103 (OR = 0.69, P = 0.006), HLA-DRB1*13 (OR = 0.71, P = 5.27 × 10−4), HLA-DQB1*0603 (OR = 0.69, P = 0.007))." (PMID 28806749, 2017). "In addition to the strong reduced risk of cervical neoplasia associated with HLA-B*15, the haplotype HLA-DRB1*1301/HLA-DQB1*0603 (and in some analyses HLA-DQA1*0103) was associated with reduced risk of squamous cell cancer, adenocarcinoma, and HPV16- and HPV18-related cervical neoplasia." (PMID 28806749, 2017). "HLA‐DQA1 belongs to the alpha chain of the human major histocompatibility complex class II (MHC‐II), and the HLA‐DQA1 genotype is closely linked to susceptibility to both LUAD and squamous cell carcinoma." (PMID 41031217, 2025).
Arthritis (3 papers, 2019 to 2025). Inflammation of a joint. "PLCG2 affects neutrophil chemotaxis and inflammation in arthritis, CYP27A1 may serve as a biomarker for intervertebral disc degeneration, and HLA-DQA1 influences neutrophil-mediated immune processes." (PMID 40096134, 2025). "Moreover, our ROC curve analysis results indicated that the differential expression of HLA-DQA1 and MAPK8IP3 could be potential biomarkers of both arthritis forms." (PMID 39315289, 2024).
childhood asthma (3 papers, 2020 to 2025). "For example, highly polymorphic HLA class II genes, such as HLA-DQA1 and HLA-DRB1, are implicated in childhood asthma susceptibility and serum immunoglobulin E (IgE) production." (PMID 36118895, 2022). "However, our findings did not reveal any associations between the 6p.21 region (HLA‐B, HLA‐C, HLA‐DQA1, and HLA‐DQB) and childhood asthma, despite previous reports suggesting such an association." (PMID 40133993, 2025).
colorectal cancer (3 papers, 2020 to 2025). A primary or metastatic malignant neoplasm that affects the colon or rectum. "Also, three meQTLs have been identified in colorectal cancer GWAS: rs9271770 related with HLA-DQA1, rs3087967 related with C11orf53 and rs3802842 intronic to COLCA1 and COLCA2 genes." (PMID 34419169, 2021). "In addition, HLA-DQA1/DQA2 were recently shown to be part of a predictive MHC class II signature for patient response, albeit in circulating T cells of ICI-treated patients with colorectal cancer (CRC) and patients with HNSCC." (PMID 40187353, 2025).
depression (3 papers, 2022 to 2025). "In fact, many of the depression-associated genes that underwent positive selection in both African and South Asian populations are immune-related, such as HLA-DQA1, HLA-DQB1, and MGAT4C." (PMID 40075226, 2025).
keloid (3 papers, 2012 to 2024). An irregularly shaped, elevated mark on the skin caused by deposits of excessive amounts of collagen during wound healing. "Previous studies have identified significant correlations between specific Human Leukocyte Antigen (HLA) alleles, such as HLA-DRB1*15 and HLA-DQA1 and DQB1, and keloid formation, suggesting a genetic inclination towards keloid development." (PMID 39119435, 2024). "Concerning the major histocompatibility complex, it was found an association between keloid and HLA-DRB1* 15 (among Caucasians), HLA-DQA1* and DQB1* (among Chinese)." (PMID 23259072, 2012).
Löfgren syndrome (3 papers, 2023 to 2025). "Another SNP near HLA-DQA1 (rs2187668) is significantly associated with Lofgren’s syndrome and HLA-DRB1*04:01 with ocular sarcoidosis in EDs." (PMID 38390497, 2023). "HLA-B*08:01, HLA-C*07:01, HLA-DRB1*03:01, HLA-DQA1*05:01, and HLA-DQB1*02:01 variants associated with Löfgren’s syndrome, a more benign phenotype." (PMID 37153085, 2023).
lung squamous cell carcinoma (3 papers, 2014 to 2024). "For lung squamous cell carcinoma, 9 genes were causally related, comprising U91328.19, FLOT1, LINC00243, HLA-DQA1, HLA-DQB1, HLA-DQB1-AS1, HLA-DQB2, ZNF483 and BLOC1S2." (PMID 38834983, 2024).
lymphoma (3 papers, 2013 to 2024). A malignant (clonal) proliferation of B- lymphocytes or T- lymphocytes which involves the lymph nodes, bone marrow and/or extranodal sites. "Significantly increased allele frequencies of HLA-DQA1*01:03 and HLA-DQB1*06:01 have also been reported in lymphoma." (PMID 38593173, 2024). "Among these binding sites, cell culture experiments using lymphoma B cells identified an X box-like element named XL9 between the two diametrically transcribed genes HLA-DRB1 and HLA-DQA1." (PMID 30212590, 2018).
nephrotic syndrome (3 papers, 2016 to 2025). A collection of symptoms that include severe edema, proteinuria, and hypoalbuminemia; it is indicative of renal dysfunction. "Recently, a study among 214 children with steroid-sensitive nephrotic syndrome from South Asia, specifically Sri Lanka, reported HLA-DQA1 missense coding variants as possible candidate loci based on exome array in case–control study compared to 149 healthy controls." (PMID 27148508, 2016). "Previous smaller studies in Chinese and Japanese children have also reported association between variants in HLA-DQ3, HLA-DQ8, HLA-DR, HLADQW2, HLA-DQA1, and HLA-DQB1 in nephrotic syndrome." (PMID 27148508, 2016). "Both HLA-DQA1 and HLA-DQB1 have been linked to steroid-sensitive nephrotic syndrome, and our observed association might provide a missing link between the HLA locus and this syndrome." (PMID 34822396, 2021).
viral infection (3 papers, 2016 to 2024). "In humans, specific alleles of the HLA-DPA1, HLA-DQA1 and HLA-DRB1 loci have been associated with viral infections." (PMID 27812212, 2016). "Furthermore, both the upregulation (KIR2DL5A/B) and downregulation (HLADQA1 and HLADQB1) of genes associated with antigen presentation suggest a heightened immune response, potentially reflecting persistent immune activation following viral infection." (PMID 39435656, 2024). "FDR analysis using all p-values obtained a minimum q-value of 27% for the associations with the four lowest p-values, namely HLA-DQB1 with sepsis infection, HLA-DQA1 with other infections, HLA-DPB1 with CNS infection and HLA-DQB1 and viral infection." (PMID 34059071, 2021).
vitiligo (3 papers, 2019 to 2023). Generalized well circumscribed patches of leukoderma that are generally distributed over symmetric body locations and is due to autoimmune destruction of melanocytes. "Using Beagle 4.1, we successfully imputed the SNV, CNV, two–digit and four–digit alleles of HLA genes (HLA-A, HLA-B, HLA-C, HLA-DQA1, HLA-DQB1, HLA-DPA1, HLA-DPB1, HLA-DRB1) and amino acids of 2810 vitiligo subjects (1117 cases, 1693 controls) and 2739 SLE subjects (1,693 controls and 1,046 cases)." (PMID 35082778, 2021). "To dissect the relative contributions of rs149554018, rs9271597, and the classical HLA alleles to vitiligo risk, we compared logistic regression models with haplotypes defined by different combinations of rs145954018, HLA-DRB1*13:01, rs9271597, HLA-DQA1*01:03, and HLA-DQB1*06:03." (PMID 30674883, 2019).